SNORD115-1 (small nucleolar RNA, C/D box 115-1)
Synonyms: HBII-52-1; RNHBII52
Gene: Small nucleolar RNA gene on chromosome 15 (25,170,723 to 25,170,804, forward strand). Ensembl gene ENSG00000201831.
Gene Ontology:
Biological process: RNA processing
Cellular component: nucleolus
Homologues: Orthologues: chimpanzee SNORD115 (99% identical), macaque SNORD115 (95% identical). Paralogues in human: SNORD115-13 (98% identical), SNORD115-12 (96% identical), SNORD115-16 (96% identical), SNORD115-40 (96% identical), SNORD115-9 (96% identical), SNORD115-10 (95% identical), SNORD115-11 (95% identical), SNORD115-20 (95% identical), SNORD115-21 (95% identical), SNORD115-29 (95% identical), SNORD115-36 (95% identical), SNORD115-42 (95% identical), and 37 more.